ENPP2 (ectonucleotide pyrophosphatase/phosphodiesterase 2)
Diseases named in the same sentence as ENPP2 in open-access papers (continued):
Sharing a sentence is not in itself a finding about the gene and the disease.
cancer (continued). "Our findings contribute to the understanding of methylation events and regulatory mechanism of ENPP2 in cancer and provide a full description of DMCs to be further validated in functional and clinical studies." (PMID 34769391, 2021). "In the present study we adopted a bioinformatic in silico approach using publicly available datasets from healthy tissues and different cancer tissues and cell lines to analyze methylation patterns of ENPP2." (PMID 34769391, 2021). "We postulate that regulating Enpp2 improves DC migration to lymph nodes, thus improving the effectiveness of cancer vaccines based on DC." (PMID 34829956, 2021). "ENPP2 contains 26 introns and 27 exons and is located in the human chromosomal region 8q24, a region with frequent genetic alterations in many cancers." (PMID 34769391, 2021). "As far as HCC is concerned, our analysis showed upregulation of expression in HCC in relation to normal liver, showing a TSS and 1st exon methylation-independent and a cancer type-specific role of ENPP2 expression regulation." (PMID 34769391, 2021). "Enpp2 is an ectoenzyme expressed and secreted by many cell types, and plays roles in blood vessel formation, cancer cell migration, insulin resistance in muscle cells, and homing and inflammatory responses by lymphocytes." (PMID 34829956, 2021). "Based on our findings, three cancer entities presenting the highest number of DMCs were selected for further study, in order to confirm altered ENPP2 methylation in larger cohorts and correlate them with expression at gene and isoform levels." (PMID 34769391, 2021). "Our study provides an extended description of the methylation status of ENPP2 in health and cancer and points out specific DMCs of value as prognostic biomarkers." (PMID 34769391, 2021). "Without availability of suitable methylome datasets or targeted methylation studies of ENPP2 in each different cancer type, we cannot extrapolate conclusions between cancers." (PMID 34769391, 2021). "Based on these interesting observations, we next performed in silico analysis of ENPP2 methylation in datasets retrieved from the TCGA, focusing on those cancer types presenting the greatest number of DMCs, i.e., LC, PC and HCC." (PMID 34769391, 2021). "Analysis of cancer datasets revealed aberrant ENPP2 methylation, showing a malignant-specific profile throughout different cancer types." (PMID 34769391, 2021). "ENPP2, which encodes for the enzyme autotaxin (ATX), is overexpressed during chronic inflammatory diseases and various cancers." (PMID 31251802, 2019). "ENPP2 has also been reported to have angiogenic properties and its expression is up-regulated in several kinds of carcinomas." (PMID 22142333, 2011). "Similarly, ENPP2 (autotaxin) promotes cancer cell survival and migration by producing lysophosphatidic acid (LPA), a bioactive lipid mediator that promotes tumor cell migration and metastasis via LPAR1." (PMID 41009025, 2025). "At the epigenetic level, the increased methylation of ENPP2 may significantly contribute to unfavorable prognostic indicators in cancer and pathogenesis." (PMID 39717045, 2024). "Apart from its recognized function in cancer cells, the involvement of ENPP2 in hard and soft tissue differentiation remains unclear." (PMID 39291269, 2024). "Additionally, we prioritized secreted lysophosphatidase autotaxin (ENPP2) as another putative drug target with already established direct roles in cancer and LMW inhibitors." (PMID 37749499, 2023). "In contrast to that, in our recent work, methylation of ENPP2 1st exon in ccfDNA was found significant hypermethylated in BC patients as compared to healthy ccfDNA and it was also correlated with the cancer load, suggesting a role of ENPP2 methylation as a BC prognostic biomarker." (PMID 36358855, 2022).
cancer (continued). "Cumulative experimental results are in accordance with those from bioinformatic analysis showing hypermethylation of ENPP2 in both BC tissue and ccfDNA and a correlation with cancer aggressiveness and metastasis, suggesting its potential as a novel circulating biomarker in BC." (PMID 36358855, 2022). "We also examined differences in the methylation of ENPP2 between BrCa cancer types." (PMID 35409077, 2022). "Furthermore, in silico studies based on TCGA datasets reported high methylation of ENPP2 in BC and characterized it as a methylation-driven gene in cancer." (PMID 36358855, 2022). "Cumulatively, our experimental results are in accordance with those from bioinformatic analysis showing hypermethylation of ENPP2 in BrCa tissue and ccfDNA and a correlation with cancer aggressiveness and metastasis, suggesting its potential as a novel circulating biomarker in BrCa." (PMID 35409077, 2022). "The same correlation pattern was noticed for ENPP2 isoforms in all cancer types studied." (PMID 34769391, 2021). "Methylation and expression results via UALCAN strengthen our findings, showing that the ENPP2 gene is methylated in LC, HCC and PC and this is related to under-expression in LC and PC, suggesting a causative relationship in these two cancer types and a cancer-specific regulatory mechanism in HCC." (PMID 34769391, 2021). "However, no regulatory relation was observed between methylation and expression in HCC, as both were upregulated, pointing again to a cancer-specific methylation-independent ENPP2 regulation." (PMID 34769391, 2021). "Since then, increased expression of Enpp2 has been detected in a variety of cancers." (PMID 34829956, 2021). "mRNA expression analysis in the same samples showed increased levels in HCC in relation to normal tissues (LogFC: 0.710, FDR: 1.00 × 10−2), i.e., the opposite of LC and PC observations, suggesting a methylation-independent and a cancer type-specific regulation of ENPP2 in HCC." (PMID 34769391, 2021). "Furthermore, increased methylation of ENPP2 was connected to poor prognostic parameters in the same cancers, which was also supported by analysis of cell line datasets." (PMID 34769391, 2021). "Igfbp5, Enpp2, Ctsh, Lpl, and Tacc1 are the top five genes correlated with the E2 branch in pseudotime and all are currently under investigation as cancer biomarkers." (PMID 30418965, 2018). "In silico analysis of publicly available genomic data at The Cancer Genome Atlas indicated genetic alterations, mostly amplifications, of ENPP2 in cancer patients, with the highest rates observed in ovarian (33%), breast (20%), liver (20%), and lung (11%) carcinomas." (PMID 29951481, 2018). "Therefore, it is functionally plausible that this region contains a locus for general cancer susceptibility via cis regulation of NOV and/or ENPP2." (PMID 22142333, 2011). "In summary, this meta-analysis of nine existing GWAS for solid-cancers indicates a possible cancer risk locus on 8q24 (120,576,000-120,626,000 bp) between NOV and ENPP2, both of which are involved in carcinogenesis and have a regulatory relationship with the proto-oncogene c-MYC." (PMID 22142333, 2011). "Thus, we suggest that regulating Enpp2 may improve DC migration to LNs, thereby improving the efficacy of DC-based cancer vaccines." (PMID 34829956, 2021). "Hence, ENPP2 methylation in the identified CGs could be pursued further and be evaluated in clinical cancer samples as biomarkers of cancer progression and poor outcome." (PMID 34769391, 2021). "The genes which have been reported to involve the cancer cell invasion (ENPP2, ADCY8), dysregulated cellular metabolism (CYC1), and angiogenesis (ANGPT1), immune inhibition (ANXA3) amplified notably in the high-risk group, which might elaborate the aggressiveness and malignancy in this group." (PMID 34568069, 2021). "Similarly to Satb1 and Hoxa1, Tmeff2 and Enpp2 are up regulated in carcinomas." (PMID 21054883, 2010).
cancer (continued). "In specific, in advanced cancer, methylation of three TSS (cg04452959, cg06998282, cg14409958) and one first exon CG (cg02534163) was negatively correlated with ENPP2 expression." (PMID 35409077, 2022). "By employing an in silico approach, we have recently described ENPP2 methylation profiles in health and malignancy, showing that methylation is an active level of ATX expression regulation in cancer." (PMID 35409077, 2022). "Differential methylation analysis of ENPP2 revealed that all emerged DMCs identified in transcription-related (TSS and 1st exon) regions were hypermethylated in all three cancers compared to healthy controls, confirming the analysis of the GEO datasets." (PMID 34769391, 2021). "Here, our presented results from the cancer types studied indicate a cancer type-specific profile of ENPP2 methylation rather than a similar pan-cancer dysregulation." (PMID 34769391, 2021). "Notably, there were diverse types of cancers that amplify ENPP2, and importantly there was not a dominating overrepresentation of one cancer type in the patient cohort." (PMID 37270644, 2023). "The data from cancer databases confirmed that ENPP2 was highly expressed in HCC tissue compared within normal liver tissues, our clinical data displayed that HCC patients with high ENPP2 level normally had poor prognosis, and ENPP2 expression was positively correlated with HBV infection." (PMID 34805271, 2021). "Complete Kaplan–Meier curves and Cox analyses on all cancer entities would be required to evaluate whether or not combined expression of both ENPP2 and SDC4 could predict overall- or disease-free patients survival." (PMID 30237860, 2018).
infection (2 papers, 2019 to 2023). The state of being infected such as from the introduction of a foreign agent such as serum, vaccine, antigenic substance or organism. "Further, comparative analysis of animals with different severity to infection highlights the potential importance of genes such as perforin-1, ENPP2 and CCL20 in conferring higher resistance against AGD." (PMID 30873203, 2019).
ENPP2 also shares sentences with these, for which no sentence is quoted: glioblastoma (3 papers); Type 2 diabetes (3); asthma (2); cancers of the thyroid (2); colorectal cancer (2); Hyperglycemia (2); lupus nephritis (2); soft tissue sarcoma (2); acute myeloid leukemia (1); adenocarcinoma (1); adult-onset Still disease (1); age-related hearing loss (1); aortic atherosclerosis (1); atherosclerosis (1); autoimmune disease (1); benign prostatic hyperplasia (1); bladder cancer (1); cervical squamous cell carcinoma (1); cholangiocarcinoma (1); chronic lymphocytic leukemia (1); Cirrhosis (1); colonic diseases (1); depression (1); diabetes (1); gastric cancer (1); gastrointestinal stromal tumor (1); gynecologic cancers (1); hearing loss (1); Hurler syndrome (1); Hyperinsulinemia (1).
A further 20 diseases each share a sentence with ENPP2 in 1 paper.